CXCL8 (C-X-C motif chemokine ligand 8)
Diseases named in the same sentence as CXCL8 in open-access papers (continued):
Sharing a sentence is not in itself a finding about the gene and the disease.
breast carcinoma (continued). "Importantly, IL-6 and CXCL-8 promoted the migration of MCF10A cells and HER2-positive breast cancer cells." (PMID 41495793, 2026). "Finally, analysis of transcriptomic databases of cancer cell lines revealed a significant correlation between CXCL8 and TGF-β1/TNF-α–regulated or effector genes in breast cancer." (PMID 40833805, 2025). "In vivo cell experiment, we confirmed that HBV infection may lead to increased expression levels of several key genes in breast cancer cell lines, including CDK2, PCNA, CCNE2, CXCL8, E2F1, and CASP3." (PMID 40697521, 2025). "HBV infection may lead to increased expression levels of several key genes in breast cancer cell lines, including CDK2, PCNA, CCNE2, CXCL8, E2F1, and CASP3." (PMID 40697521, 2025). "We found that overall correlations between TGF-β–related genes and CXCL8 across all cell lines are not significantly different compared with breast cancer cell lines alone (P = 0.52, paired t test)." (PMID 40833805, 2025). "We therefore tested whether correlations between CXCL8 expression and TNF-α or TGF-β–related genes were stronger in breast cancer cell lines relative to all the cell lines tested in DepMap." (PMID 40833805, 2025). "It is involved in breast cancer cell survival and/or proliferation, tumor-promoting, aggressiveness, tumor-promoting macrophage infiltration, CAF phenotype, inflammatory chemokine expression, such as C-X-C motif ligand 8 (CXCL8 = IL-8), and angiogenesis." (PMID 36835413, 2023). "Other CXCR2 ligands may play a more important role in breast cancer than CXCL1, for example, CXCL5/epithelial-cell-derived neutrophil activating factor 78 (ENA78) and CXCL8/interleukin-8 (IL-8), whose expression is increased in breast tumors." (PMID 37108425, 2023). "Cultivating three different types of breast cancer cell lines by CM derived from young and senescent HPMCs, it was observed that the secretory levels of pro-angiogenic agents, including CXCL1, CXCL8, the hepatocyte growth factor (HGF), and the VEGF, were significantly increased in cancer cells." (PMID 37046588, 2023). "CXCR1, one of the receptors for CXCL8 (IL‐8), is identified in ALDH1‐positive breast cancer CSCs." (PMID 36694633, 2023). "In addition, we detected the mRNA levels of CXCL1-3 and CXCL8 in cancer tissues, and CXCR2 and LIF in adipocytes adjacent to breast cancer of clinical breast cancer specimens." (PMID 35280694, 2022). "Therefore, we believe that breast cancer cells express more CXCL1, CXCL2, CXCL3, and CXCL8 after co-culturing with adipocytes." (PMID 35280694, 2022). "Importantly, we found that breast cancer-derived CXCL1-3 and CXCL8 bind to the receptor CXCR2 and activate the ERK1/2 signaling pathway to initiate the expression of LIF by activating transcription factors NF-κB and Stat3 in CAAs in paracrine manner." (PMID 35280694, 2022). "Similarly, TCGA data analysis revealed elevated expression patterns of CXCL8, CXCL1, and CXCL5 in ER- breast cancer specimens." (PMID 33912188, 2021). "Indeed, many of the soluble factors including CXCL8, G-CSF, and GM-CSF, secreted abundantly from the M4 and MDA-MB-231metastatic breast cancer cells, are known to have pro-survival effect on neutrophils." (PMID 33912188, 2021). "Breast cancer, for example, is characterized by an elevated secretion of proinflammatory cytokines (IL-1, TNF-α, IL-6) or anti-inflammatory cytokines (IL-10), chemokines and chemokine receptors (CXCL8, CXCR4), and angiogenic factors (VEGF)." (PMID 35111484, 2021).
breast carcinoma (continued). "In a model of breast cancer, the secretion of IL-1β and TNF-α by transformed cells and immune cells, activates in bone marrow MSCs NF-κB pathway and chemokine secretion like CCL2 and CXCL8/IL-8 that favor an inflammatory TME promoting monocyte migration." (PMID 34680425, 2021). "In addition, breast cancer patients with high expression of ATAT1 and MAPK8, RASSF1, BCL2, CXCL8, and FGF1, had a poor prognosis." (PMID 34199510, 2021). "To identify the pro-carcinogenic role of KTN1 in vivo, we assessed the effects of KTN1 overexpression, and CXCL8 knockdown by siRNA oligos of cholesterol and dimethoxy-modified in KTN1 overexpressed cells on MDA-MB-231 xenograft mammary tumor growth in NOD/SCID/IL2rγ null (NSG) mice." (PMID 34219129, 2021). "In addition, CCL2 was shown to activate the STAT3 and NOTCH1 pathways and macrophages-derived chemokine CXCL8 increases CSCs-like populations and enhances mammosphere formation via activation of AKT/mTOR signaling in renal and breast cancer." (PMID 33414786, 2020). "We used the STRING bioinformatic tool to find biological processes associated with the gene products that we analyzed for their prognostic impact on breast cancer, namely IKKα (CHUK), IKBKB, p50/NFKB1, p65/RELA, NIK (MAP4K4), p52 (NFKB2), RELB, IL-8 (CXCL8), IL6, and MMP-1." (PMID 31602271, 2019). "Compared with patients with no metastasis, those with breast cancer and bone metastases demonstrate increased CXCL8 levels." (PMID 31788042, 2019). "CXCL8 has been reported to play multiple roles in cancer, such as increasing proliferation, angiogenesis, and metastases, as well as in mammosphere formation in HER2-positive breast cancer." (PMID 31330794, 2019). "However, findings from tumor research show that CXCL8 stimulation upregulates CXCR4 levels in prostate carcinoma cells and CXCR4 drives tumor invasion and metastasis via activating CXCR2 in breast cancer." (PMID 31885605, 2019). "The tumor-promoting effect of CXCL8 is further strengthened by the observation that, while this chemokine promotes EMT, EMT by itself promotes CXCL8 secretion, thus producing a loop-reinforcing cascade, which was demonstrated in colon and breast cancer cells." (PMID 29977225, 2018). "In addition, CXCL8/IL8 signalling has been shown to convey chemotherapy resistance in at least prostate cancer, breast cancer, and colorectal cancer." (PMID 30126117, 2018). "Taken together, our data highlighted that CUL1 regulated EZH2 expression to promote the production of autocrine expression of the autocrine cytokines CXCL8 and IL11, and finally significantly aggravating the breast cancer cell metastasis through the PI3K–AKT–mTOR signaling pathway." (PMID 30578411, 2018). "Second, six genes, CHI3L1, CXCL8, FOXC2, SERPINE1, SFRP2, and TF, which are grouped within the highest enrichment GO term, “positive regulation of angiogenesis”, have been reported to play roles in various cancer processes, including breast cancer." (PMID 30205506, 2018). "Our data indicated that CXCL8 and IL11 contributed to CUL1-regulated breast cancer metastasis." (PMID 30578411, 2018). "In mechanism, the human gene expression profiling was used to determine global transcriptional changes in MDA-MB-231 cells, and we identified autocrine expression of the cytokines CXCL8 and IL11 as the target genes of CUL1 in breast cancer cell migration, invasion, metastasis, and angiogenesis." (PMID 30578411, 2018). "IL-17 promotes tumor proliferation, survive and metastasis by up regulating angiogenesis factors VEGF, CXCL8, MMP2 and MMP9, while at the same time, it significantly suppresses apoptosis in several human breast carcinoma cell lines, such as 4T1, MDA-MB-231 cells." (PMID 26313265, 2015). "Here, we identified the impact of TNF-α and IL-1β on the inflammatory phenotype of CAFs and MSCs by determining the expression of inflammatory chemokines that are well-characterized as pro-tumorigenic in breast cancer: CCL2 (MCP-1), CXCL8 (IL-8) and CCL5 (RANTES)." (PMID 25928089, 2015).
breast carcinoma (continued). "Additionally, many markers we observed that defined our monocyte clusters (FABP5, FN1, IL1RN, CCL3, CCL4, CXCL8, CXCL3, IL1B) during transient, short-term CM stimulation, were elevated in either PD-L1pos or PD-L1neg TAMs isolated and sequenced from breast cancer." (PMID 40176808, 2025). "Finally, breast cancer patients with bone metastases were shown to have elevated CXCL8 plasma levels compared to patients without metastasis, and the CXCL8 plasma levels correlated with increased bone resorption." (PMID 31572390, 2019). "Thus, ectopic expression of CXCL8, stimulated by IL-1β and TNF-α, could exacerbate the metastatic potential of breast cancer." (PMID 31788042, 2019). "Since CXCL8 is a prominent regulator of BCSC activity, a combined treatment of CXCR2 inhibitors and current HER2-targeted therapies is predicted to be an effective regimen to decrease CSC activity and increase survival in HER2-positive patients with breast cancer." (PMID 31788042, 2019). "While it may not substantially alter the proliferative ability of mammary carcinoma cells, CXCL8 heightens the invasiveness and miration of both murine and human breast tumors, triggers epithelial–mesenchymal transition (EMT), and supports the self-renewal capacity of BC stem cells (BCSCs)." (PMID 40092996, 2025). "The signature profile analysis of CXCL8, IL6, and NFKB1 revealed a higher mRNA expression in non-responder breast cancer patients (p = 0.015)." (PMID 39336151, 2024). "CXCL8 (p = 0.12), IL6 (p = 0.022), and NFKB1 (p = 0.0097) mRNA levels were higher in breast cancer patients who did not respond to chemotherapy treatment." (PMID 39336151, 2024). "Estrogen receptor (ER) negative breast cancers exhibit increased expression of inflammatory chemokines CCL2, CCL4, and CXCL8 compared to ER+ breast cancers and this correlates with the phenotype of the inflammatory infiltrate in the tumor." (PMID 28143493, 2017).
Sepsis (528 papers, 1992 to 2026). Sepsis is defined as life-threatening organ dysfunction caused by a dysregulated host response to infection. "CXCL8 expression in sepsis is profoundly increased and associated with sepsis’s progression and prognosis." (PMID 36451225, 2022). "The expression levels of serum CXCL8 and ET-1 in sepsis patients with heart failure are significantly increased, and both are risk factors for heart failure in sepsis patients." (PMID 36065195, 2022). "The results showed that CXCL8 and ET-1 were independent risk factors for sepsis complicated with heart failure (P < 0.05)." (PMID 36065195, 2022). "A defining feature of those infants who develop infection is a lower level of CXCL8-producing T cells initially, thus identifying a potential biomarker for identifying infants at greater risk of sepsis." (PMID 32152273, 2020). "In addition, quercetin is a component of the Chinese herbal extract Xuebijing, and it has been shown to regulate C-X-C Motif Chemokine Ligand 8 (CXCL8), thus posing as a potential avenue for treatment against sepsis-associated kidney injury." (PMID 39126050, 2024). "CXCL8 and ET-1 were independent risk factors for sepsis complicated with heart failure (P < 0.05)." (PMID 36065195, 2022). "Besides, CXCL8 and ET-1 were risk factors for sepsis patients complicated with heart failure in the logistic regression analysis." (PMID 36065195, 2022). "Hence, CXCL8 might be implicated in neutrophil-induced tissue damage, a typical lesion observed during sepsis (Shen and others 2017)." (PMID 35674675, 2022). "Biomarkers have shown significant promise in prognostication following acute respiratory distress syndrome (ARDS) and sepsis: interleukin (IL)-6, IL-8 (otherwise known as C-X-C motif ligand-8 or CXCL8), and tumor necrosis factor receptor 1 (TNFR1)." (PMID 40433392, 2025). "CXCL8, as a key pro-inflammatory chemokine, plays an important role in sepsis-related acute kidney injury." (PMID 40166075, 2025). "In the CLP-induced sepsis kidney injury model, the IL-2 gene exhibited low expression, whereas the CXCL8, IL-1β, TNF, IL-6, and IL-10 genes demonstrated high expression levels." (PMID 40166075, 2025). "The CoIP results confirmed direct interactions between MMP8, MMP9, ARG1, and CXCL8, substantiating their roles in sepsis-related inflammatory pathways." (PMID 39560539, 2024). "In fact, enrichment of the repressive mark H3K9me2 was increased in promoters of TNFA, IL-1B, CXCL8, and IL-17 at 1 dpb in patients that develop sepsis." (PMID 39768289, 2024). "During the onset of sepsis, the neutrophils recognize the chemotactic signals from CXCL8, promoting their migration to sites of infection and contributing to the series of responses associated with sepsis development." (PMID 38281996, 2024). "Decreased neutrophil migration towards CXCL8 is seen especially in patients with severe sepsis; this chemotactic CXCL8 effect seems to be a part of a more complex dysregulated phenotype also including defects in NETosis and delayed apoptosis." (PMID 37048076, 2023). "The migratory responses to formylated peptides, LTB4 and CXCL8 are reduced, and neutrophil C5aR expression reaches an early peak during sepsis before a gradual decline." (PMID 37048076, 2023). "The increase in inflammatory factor CXCL8 leads to the damage of myocardial cells, which further promotes the occurrence of complicated heart failure in sepsis patients." (PMID 36065195, 2022). "The chemokine receptor CXCR2 and its ligands, especially CXCL8, are crucial mediators for the progression of liver inflammation and liver failure in sepsis." (PMID 36451225, 2022).
Sepsis (continued). "Even though most of the pro-inflammatory cytokines in sepsis were lower than those recorded in malaria, levels of CXCL8/IL-8 and IL-17 were comparable between the malaria and sepsis group." (PMID 35811678, 2022). "CXCL8 (also named IL-8) is found at high concentrations in patients with sepsis (MERA and others 2011; Surbatovic and others 2015)." (PMID 35674675, 2022). "The expression levels of serum CXCL8 and ET-1 in patients complicated with heart failure were higher than those in patients with sepsis alone (P < 0.05)." (PMID 36065195, 2022). "The results showed that the expression level of CXCL8 in serum of patients with sepsis and heart failure was higher than that of patients with sepsis alone, which was consistent with those of previous studies." (PMID 36065195, 2022). "In the future, the predictive value of serum CXCL8 and ET-1 in sepsis patients complicated with heart failure will be further evaluated, and compared with ultrasonography to explore their clinical application value." (PMID 36065195, 2022). "According to Pearson's correlation analysis, serum CXCL8 of sepsis patients complicated with heart failure was positively correlated with ET-1 (r = 0.531, P < 0.05)." (PMID 36065195, 2022). "It is further suggested that CXCL8 and ET-1 can not only reflect the severity of sepsis patients, but also be used as important biomarkers for sepsis patients complicated with heart failure, and their predictive value needs further verification." (PMID 36065195, 2022). "In view of this, this study aims to provide a reference for disease prevention by detecting serum CXCL8, ET-1, and cardiac function parameters in sepsis patients complicated with heart failure, and analyzing the correlation between these indexes." (PMID 36065195, 2022). "It is suggested that the increase of serum CXCL8 expression level is significantly related to the heart failure of sepsis patients." (PMID 36065195, 2022). "Several chemokines have been identified as biomarkers for sepsis, such as CXCL8, CXCL13, CCL2, and CCL8." (PMID 32500306, 2020). "We have proceeded to show that stimulation of NOD1 in human endothelial cells induces multiple chemokine and cytokine response genes that are implicated in sepsis including CXCL6, CXCL8, IL1-β and TNFα." (PMID 22870324, 2012). "Indeed, in addition to its well-established role as a neutrophil chemoattractant through CXCR1 and CXCR2, IL-8 (CXCL8) acts as a stage-dependent mediator in sepsis." (PMID 41268545, 2025). "CXCL8, one of the most intensively studied chemokines, is significantly elevated in the serum of septic patients with concomitant heart failure than in patients with sepsis alone." (PMID 40520010, 2025). "The aim of this research was to investigate the effects of epidermal growth factor receptor (EGFR) monoclonal antibody-modified chemokine (C-X-C motif) ligand 8 (CXCL8) overexpression of macrophage (CXCL8@M)-derived exosomes miR-126a-3p (EGFR@CXCL8@exo-miR-126a-3p) on sepsis ALI." (PMID 41293091, 2025). "Interestingly, the repressive mark H3K9me2 was significantly enriched in TNFA, IL-1B, CXCL8, and IL-17 gene promoters at 1 dpb in patients who developed sepsis." (PMID 39768289, 2024). "Specifically, both sepsis and recurrence groups (groups A and B, respectively) exhibited significant variation in the CXCL-8 marker than the group of patients with unknown complications (group C)." (PMID 37835833, 2023). "CXCL8 and ET-1 may become potential therapeutic targets for sepsis complicated with heart failure, which is of great significance to the formulation and adjustment of treatment plan for patients." (PMID 36065195, 2022). "Serum CXCL8 was positively correlated with ET-1 in patients with sepsis complicated with heart failure (r = 0.531, P < 0.05), and the two were positively correlated with SOFA score and APACHE II score (P < 0.05) and were negatively correlated with LVEF, SV, CO, and CI (P < 0.05)." (PMID 36065195, 2022).